TOPBP1 (DNA topoisomerase II binding protein 1)
Description:
Scaffold protein that acts as a key protein-protein adapter in DNA replication and DNA repair. Composed of multiple BRCT domains, which specifically recognize and bind phosphorylated proteins, bringing proteins together into functional combinations. Required for DNA replication initiation but not for the formation of pre-replicative complexes or the elongation stages (By similarity). Necessary for the loading of replication factors onto chromatin, including GMNC, CDC45, DNA polymerases and components of the GINS complex (By similarity). Plays a central role in DNA repair by bridging proteins and promoting recruitment of proteins to DNA damage sites. Involved in double-strand break (DSB) repair via homologous recombination in S-phase by promoting the exchange between the DNA replication factor A (RPA) complex and RAD51. Mechanistically, TOPBP1 is recruited to DNA damage sites in S-phase via interaction with phosphorylated HTATSF1, and promotes the loading of RAD51, thereby facilitating RAD51 nucleofilaments formation and RPA displacement, followed by homologous recombination. Involved in microhomology-mediated end-joining (MMEJ) DNA repair by promoting recruitment of polymerase theta (POLQ) to DNA damage sites during mitosis. MMEJ is an alternative non-homologous end-joining (NHEJ) machinery that takes place during mitosis to repair DSBs in DNA that originate in S-phase. Recognizes and binds POLQ phosphorylated by PLK1, enabling its recruitment to DSBs for subsequent repair. Involved in G1 DNA damage checkpoint by acting as a molecular adapter that couples TP53BP1 and the 9-1-1 complex. In response to DNA damage, triggers the recruitment of checkpoint signaling proteins on chromatin, which activate the CHEK1 signaling pathway and block S-phase progression. Acts as an activator of the kinase activity of ATR. Also required for chromosomal stability when DSBs occur during mitosis by forming filamentous assemblies that bridge MDC1 and tether broken chromosomes during mitosis. Together with CIP2A, plays an essential role in the response to genome instability generated by the presence of acentric chromosome fragments derived from shattered chromosomes within micronuclei. Micronuclei, which are frequently found in cancer cells, consist of chromatin surrounded by their own nuclear membrane: following breakdown of the micronuclear envelope, a process associated with chromothripsis, the CIP2A-TOPBP1 complex tethers chromosome fragments during mitosis to ensure clustered segregation of the fragments to a single daughter cell nucleus, facilitating re-ligation with limited chromosome scattering and loss. Recruits the SWI/SNF chromatin remodeling complex to E2F1-responsive promoters, thereby down-regulating E2F1 activity and inhibiting E2F1-dependent apoptosis during G1/S transition and after DNA damage.
Synonyms: KIAA0259; TOP2BP1; Dpb11
Tractability: Antibody: its Gene Ontology location is reachable by antibodies, with high confidence. PROTAC: UniProt records ubiquitination sites on it; ubiquitination databases record sites on it.
Target class: Enzyme
Gene: Protein-coding gene on chromosome 3 (133,598,175 to 133,662,380, reverse strand). Ensembl gene ENSG00000163781.
Subcellular location: Nucleus; Chromosome; Cytoplasm, cytoskeleton, microtubule organizing center, centrosome; Cytoplasm, cytoskeleton, spindle pole
Subcellular location (Human Protein Atlas): Nuclear bodies; Nucleoplasm; Plasma membrane
Pathways (Reactome):
DNA Repair: HDR through Single Strand Annealing (SSA); Presynaptic phase of homologous DNA pairing and strand exchange; Processing of DNA double-strand break ends
Cell Cycle: G2/M DNA damage checkpoint
Disease: Impaired BRCA2 binding to RAD51
Gene Ontology:
Molecular function: chromatin-protein adaptor activity; identical protein binding; phosphorylation-dependent protein binding; protein binding; protein serine/threonine kinase activator activity
Biological process: broken chromosome clustering; chromosome organization; DNA damage checkpoint signaling; DNA damage response; DNA replication checkpoint signaling; double-strand break repair via alternative nonhomologous end joining; double-strand break repair via classical nonhomologous end joining; double-strand break repair via homologous recombination; protein localization to site of double-strand break; response to ionizing radiation; DNA repair; DNA replication initiation; homologous recombination; mitotic DNA replication checkpoint signaling; mitotic G2 DNA damage checkpoint signaling; chromatin organization
Cellular component: BRCA1-B complex; chromosome; nuclear body; nucleoplasm; nucleus; PML body; site of DNA damage; site of double-strand break; centrosome; condensed nuclear chromosome; male germ cell nucleus; spindle pole
Genetic constraint (gnomAD): Loss-of-function variants: 24 observed, 150.26 expected, observed/expected ratio (o/e) 0.16, 90% interval 0.12 to 0.22. The upper end of that interval is the gene's LOEUF score, 0.22, which puts it in group 1 of 6, group 1 being the genes least tolerant of losing a copy. Missense variants: 1,410 observed, 1,707.1 expected, observed/expected ratio (o/e) 0.83, 90% interval 0.79 to 0.86. Synonymous variants: 549 observed, 579.13 expected, observed/expected ratio (o/e) 0.95, 90% interval 0.88 to 1.02.
Gene-disease validity (ClinGen):
ClinGen rates the evidence that TOPBP1 causes each of these diseases.
pulmonary arterial hypertension (autosomal dominant): No Known Disease Relationship. Pulmonary arterial hypertension (PAH) is a group of diseases characterized by mean pulmonary artery pressure >20 mmHg and elevated pulmonary arterial resistance leading to right heart failure.
Homologues: Orthologues: chimpanzee TOPBP1 (99% identical), macaque TOPBP1 (98% identical), pig TOPBP1 (91% identical), dog TOPBP1 (90% identical), rabbit TOPBP1 (85% identical), rat Topbp1 (78% identical), mouse Topbp1 (77% identical), guinea pig TOPBP1 (75% identical), tropical clawed frog topbp1 (63% identical), zebrafish topbp1 (51% identical). Paralogues in human: SLF1 (9% identical).
Diseases named in the same sentence as TOPBP1 in open-access papers:
TOPBP1 is named in the same sentence as 38 diseases in open-access papers, as found by Europe PMC text mining. Sharing a sentence is not in itself a finding about the gene and the disease. The quoted sentences say what the papers report.
breast carcinoma (20 papers, 2010 to 2025). "Particularly, TopBP1 overexpression is found in 46 of 79 primary breast cancer tissues analyzed and is associated with high tumor grade and shorter patient survival time." (PMID 32459662, 2020). "Deregulated activity of TOPBP1 has been associated to cancer, in particular breast cancer, and it is considered a potential target for cancer therapy." (PMID 30857266, 2019). "Our earlier studies concerning TopBP1 in breast cancer showed association between SNP (rs115160714) with breast cancer risk as well as aberrant expression of this protein in breast cancer." (PMID 24346708, 2014). "In conclusion, our results showed that rs115160714 polymorphism can increase breast cancer risk and is associated with changes in TopBP1 expression." (PMID 23277395, 2013). "In this study, we demonstrated for the first time that rs115160714 in the 3′UTR region of TopBP1 gene is significantly associated with breast cancer risk." (PMID 23277395, 2013). "The DNA double strand break repair gene TOPBP1 has been suggested as a breast cancer susceptibility gene and a missense variant Arg309Cys was observed at elevated frequency in familial breast cancer cases compared to healthy controls from Finland." (PMID 21108795, 2010). "Functional TOPBP1 variants therefore represent plausible candidate breast cancer susceptibility alleles." (PMID 21108795, 2010). "The results of our earlier studies showing association between TopBP1 polymorphism and breast cancer risk prompted us to investigate whether such genetic alterations can influence the endometrial cancer risk." (PMID 24346708, 2014). "The biological function of TopBP1 and its close relation with BRCA1 prompted us to investigate whether alterations in the TopBP1 gene can influence the risk of breast cancer." (PMID 23277395, 2013). "The aim of this study was to examine the association between five polymorphisms (rs185903567, rs116645643, rs115160714, rs116195487, and rs112843513) located in the 3′UTR region of the TopBP1 gene and breast cancer risk as well as allele-specific gene expression." (PMID 23277395, 2013). "Our data suggested that increased level of TopBP1 protein might be associated with progression of hereditary breast cancer." (PMID 23277395, 2013). "Taking into account the role of TopBP1 in DNA damage response we were interested in exploring whether TopBP1 SNP–breast cancer association varied according to smoking status or alcohol consumption." (PMID 23277395, 2013). "Our study raises a possibility that a genetic variation of TopBP1 may be implicated in the etiology of breast cancer." (PMID 23277395, 2013). "In summary, the association between TopBP1 mRNA and protein expression and aggressive behavior of breast cancer could have a potential therapeutic implication." (PMID 22544570, 2012). "Further research may reveal whether any TOPBP1 gene variants can contribute to hereditary breast cancer risk." (PMID 21108795, 2010). "TOPBP1 is overexpressed in multiple malignancies, including breast cancer, lung cancer, and ovarian cancer." (PMID 38762174, 2024). "DNA topoisomerase II-binding protein 1 (TopBP1) serves as a scaffold to assemble protein complexes in a phosphorylation-dependent manner via its multiple breast cancer C-terminal (BRCT) repeats." (PMID 35875060, 2022). "We also compared their levels with the endogenous TopBP1 levels in eight primary breast cancer fresh-frozen samples that have been shown to express high levels of TopBP1 in a prior study (right two panels)." (PMID 33556369, 2021). "To further investigate this possibility, we stably knocked down TopBP1 to various degrees in MDA-MB468 cells that express TopBP1 at the highest level among a panel of breast cancer cell lines." (PMID 33556369, 2021). "They detected significant associations of some haplotypes of BABAM1, ATM, CTIP (RBBP8), TOPBP1, BRIP1, BRE and RAD50 with the modification of breast cancer risk." (PMID 30823486, 2019).
breast carcinoma (continued). "Thus, polymorphisms in TopBP1 gene may modify the relationship between breast cancer and smoking." (PMID 23277395, 2013). "Immunohistochemical analysis of TopBP1 level demonstrated that this protein was expressed almost exclusively in nuclei of the normal breast epithelium while in breast cancer samples TopBP1 was detected in nucleus and/or in cytoplasm." (PMID 23277395, 2013). "The level of TopBP1 mRNA appeared to be lower in poorly differentiated (III grade) hereditary breast cancer in comparison with moderately (II grade) and well-differentiated cancer (I grade)." (PMID 23277395, 2013). "Analysis of TopBP1 protein expression in feline and canine mammary neoplasms revealed that most TopBP1 immunohistochemical staining was nuclear but both nuclear and cytoplasmic staining was observed as the degree of malignancy increased." (PMID 23277395, 2013). "Expression of TopBP1 protein was found to be significantly increased in poorly differentiated breast cancer (III grade) (p < 0.05)." (PMID 22544570, 2012). "In 10 of 30 moderate differentiated breast cancers expression of TopBP1 was observed only in the nuclear fraction." (PMID 22544570, 2012). "Our results obtained by immunohistochemical and Western blot analyses showed higher level of TopBP1 protein in breast cancer samples compared with normal breast tissues." (PMID 22544570, 2012). "TopBP1 mRNA expression was observed in all of 24 (100 %) normal breast tissue samples and in 97 of 127 (76.4 %) breast cancer samples." (PMID 22544570, 2012). "In this study we examined the relationship between expression of TopBP1 gene at the mRNA and protein level and clinicopathological parameters of hereditary breast cancers." (PMID 22544570, 2012). "We also found that expression of TopBP1 mRNA contrary to TopBP1 protein level was inversely correlated with histological grade of hereditary breast cancers." (PMID 22544570, 2012). "Significantly lower TopBP1 mRNA level in the poorly differentiated (grade III) familial breast cancer compared with moderately (grade II, p < 0.01) and well-differentiated cancer (grade I, p < 0.001) was noted." (PMID 22544570, 2012). "In this study we aimed to investigate expression of TopBP1 gene at mRNA and protein level in hereditary breast cancer." (PMID 22544570, 2012). "The expression of TopBP1 gene at the mRNA level in normal breast tissue and hereditary breast cancer was estimated by real-time quantitative PCR analysis with GAPDH gene applied as a reference." (PMID 22544570, 2012). "The expression level of TopBP1 protein was determined in 127 breast carcinoma samples using immunohistochemical technique." (PMID 22544570, 2012). "TopBP1 protein was found in all nuclear and one cytoplasmic fraction of analyzed breast cancer in grade I. Pattern of TopBP1 protein expression in well-differentiated breast cancer was similar to normal breast tissue samples." (PMID 22544570, 2012). "The level of TopBP1 mRNA appeared to be lower in poorly differentiated (III grade) hereditary breast cancer in comparison with moderately (II grade) and well-differentiated cancer (I grade) (p < 0.05 and p < 0.001 respectively)." (PMID 22544570, 2012). "Level of TopBP1 mRNA was significantly higher in normal breast tissues than in breast cancer specimens (p < 0.01)." (PMID 22544570, 2012). "TOPBP1 encodes a protein that shares homology to BRCA1, is aberrantly expressed in breast carcinomas and has a critical role in DNA damage and replication checkpoint pathways." (PMID 21108795, 2010). "Reduced or aberrantly localized TopBP1 expression has been observed in a significant proportion of breast cancer specimens." (PMID 21108795, 2010). "Furthermore, OTUB1 and OTUD6A deubiquitinated and stabilized CHK1 and TopBP1, which regulated DNA damage and repair and promoted radiation resistance in lung and breast cancer, respectively." (PMID 40469292, 2025).
breast carcinoma (continued). "Additionally, blocking the PHF8-TOPBP1 (DNA topoisomerase II binding protein 1) connection would trigger the vulnerability to chemotherapeutics in breast cancer." (PMID 37174034, 2023). "Moreover, CIP2A has recently been shown to interact with the TOPBP1 complex during mitosis in breast cancer cells." (PMID 36999590, 2023). "The biological function of TopBP1 and its close relation with BRCA1 prompted us to investigate whether genetic alterations in the TopBP1 gene can influence the risk of breast cancer." (PMID 23277395, 2013). "However, the immunohistochemistry and Western blot analyzes showed significantly increased of TopBP1 protein level in poorly differentiated breast cancer (III grade)." (PMID 23277395, 2013). "In present study we tested the effect of SNPs potentially located in the 3′UTR (3′untranslated region) region of the TopBP1 gene and listed in NCBI’s (National Center for Biotechnology Information) SNP database on breast cancer risk as well as on allele-specific mRNA/protein expression." (PMID 23277395, 2013). "Expression of TopBP1 gene at the mRNA level was observed in 62.0 % (23/37) of poorly differentiated breast cancer (grade III), whereas nearly 80 % of tumors in I and II grade demonstrated detectable TopBP1 mRNA (78.6 % (11/14) and 78.9 % (60/76), respectively)." (PMID 22544570, 2012). "Therefore, the current study was aimed at investigating expression of TopBP1 gene at mRNA and protein level in hereditary breast cancers." (PMID 22544570, 2012). "Our results showing inverse correlation between TopBP1 mRNA and protein levels in breast cancers seem to confirm this hypothesis." (PMID 22544570, 2012). "Moreover, we observed higher TopBP1 protein level in the poorly differentiated breast cancers compared to moderately and well-differentiated cancers." (PMID 22544570, 2012). "Thus, positive expression of TopBP1 mRNA in normal tissue was more frequently observed compare to breast cancer samples (p < 0.05)." (PMID 22544570, 2012). "Altogether, we find no general association of the TOPBP1 Arg309Cys variant with breast cancer risk, and the direction of the marginally significant association with bilateral disease in our study is in conflict with the original data." (PMID 21108795, 2010). "However, the aberrant expression of TopBP1 protein in breast cancer was shown." (PMID 23277395, 2013). "TopBP1 polymorphism did not changed alcohol consumption-breast cancer risk relationship." (PMID 23277395, 2013). "Our results thus do not support the increased risk for Arg309Cys, though it cannot be ruled out that TOPBP1 variants exist which may confer an increased susceptibility towards breast cancer." (PMID 21108795, 2010). "In breast cancer, OTUD6A increases the stability of TopBP1 by cleaving the K48-type polyUb chain, thereby initiating the DDR pathway, leading to tumor cell proliferation, migration, and invasion." (PMID 41050073, 2025). "The study revealed that in breast cancer, OTUD6A stabilized DNA topoisomerase 2 binding protein 1 (TopBP1) by inhibiting its K48-Ub." (PMID 40469292, 2025). "First, co-IP with cellular extracts collected from breast cancer cell MDA-MB-231 confirmed that auranofin impaired TOPBP1-PHF8 and TOPBP1-FANCJ interactions." (PMID 41392982, 2025). "Immunoblotting analysis showed that breast cancer cells expressed higher levels of HTATSF1 and TOPBP1 compared to MCF10A and HMECs, and HTATSF1 pS748 was also upregulated in these cancer cells." (PMID 38762174, 2024). "Therefore, TopBP1 may be an important prognostic marker for aggressive subgroups of breast cancer." (PMID 22544570, 2012). "In 6 of 16 breast cancer in grade III, TopBP1 protein was reveals in both the nuclear and cytoplasmic fractions." (PMID 22544570, 2012).
breast carcinoma (continued). "Patients with overexpression of TopBP1 tend to have higher grades of breast cancer and negative estrogen receptor status compared with those without overexpression of this protein and have significantly shorter overall survival time." (PMID 23277395, 2013). "In the case of four poorly differentiated breast cancer, TopBP1 protein was in the nuclear fraction and was absent in the cytoplasmic fraction." (PMID 22544570, 2012). "In the literature there is no data concerning expression of TopBP1 at mRNA level in normal and cancerous tissues and only a few studies have examined the expression of TopBP1 protein in female breast cancer." (PMID 22544570, 2012). "Moreover, we found that auranofin did not elicit a more pronounced viability defect in TOPBP1-depleted breast cancer cells." (PMID 41392982, 2025). "Phenocopying the edited breast cancer cells, we found that TOPBP1 and RAD51 could not be efficiently deposited on damaged chromatin in sgRNA-1 and sgRNA-2 lung cancer cells." (PMID 38762174, 2024). "In contrast to HTATSF1/Wt and HTATSF1/S748D, HTATSF1/S748A mutation could not efficiently rescue HTATSF1 depletion-induced defects, upon cisplatin and irradiation treatment, including TOPBP1 recruitment and RAD51 loading at γH2AX-marked damaged chromatin in EdU-labeled S-phase breast cancer cells." (PMID 38762174, 2024). "Moreover, patients with overexpression of TopBP1 tend to have higher grades of breast cancer than those without overexpression of TopBP1." (PMID 22544570, 2012). "Indeed, HTATSF1/S748A, which does not interact with TOPBP1, could not rescue HTATSF1 depletion–induced repair defects and chemotherapeutic sensitivity in breast cancer cells." (PMID 38762174, 2024).